RBL1 (RB transcriptional corepressor like 1)
Description:
Key regulator of entry into cell division. Directly involved in heterochromatin formation by maintaining overall chromatin structure and, in particular, that of constitutive heterochromatin by stabilizing histone methylation (By similarity). Recruits and targets histone methyltransferases KMT5B and KMT5C, leading to epigenetic transcriptional repression (By similarity). Controls histone H4 'Lys-20' trimethylation (By similarity). Probably acts as a transcription repressor by recruiting chromatin-modifying enzymes to promoters (By similarity). Potent inhibitor of E2F-mediated trans-activation. May act as a tumor suppressor.
Synonyms: p107; cp107; PRB1
Tractability: PROTAC: ubiquitination databases record sites on it.
Gene: Protein-coding gene on chromosome 20 (36,996,349 to 37,095,999, reverse strand). Ensembl gene ENSG00000080839.
Subcellular location: Nucleus
Subcellular location (Human Protein Atlas): Nucleoplasm
Pathways (Reactome):
Cell Cycle: Cyclin D associated events in G1; G0 and Early G1; G1/S-Specific Transcription; Transcription of E2F targets under negative control by DREAM complex; Transcription of E2F targets under negative control by p107 (RBL1) and p130 (RBL2) in complex with HDAC1
Signal Transduction: SMAD2/SMAD3:SMAD4 heterotrimer regulates transcription
Gene Ontology:
Molecular function: promoter-specific chromatin binding; protein binding; RNA polymerase II transcription regulatory region sequence-specific DNA binding
Biological process: negative regulation of cellular senescence; negative regulation of gene expression; regulation of lipid kinase activity; negative regulation of DNA-templated transcription; negative regulation of G1/S transition of mitotic cell cycle; regulation of DNA-templated transcription; regulation of cell cycle; regulation of gene expression; regulation of transcription by RNA polymerase II
Cellular component: nucleoplasm; chromatin; DRM complex; nucleus; transcription regulator complex
Genetic constraint (gnomAD): Loss-of-function variants: 72 observed, 114.96 expected, observed/expected ratio (o/e) 0.63, 90% interval 0.52 to 0.76. The upper end of that interval is the gene's LOEUF score, 0.76, which puts it in group 3 of 6, group 1 being the genes least tolerant of losing a copy. Missense variants: 1,108 observed, 1,287.7 expected, observed/expected ratio (o/e) 0.86, 90% interval 0.82 to 0.9. Synonymous variants: 395 observed, 442.78 expected, observed/expected ratio (o/e) 0.89, 90% interval 0.82 to 0.97.
Homologues: Orthologues: chimpanzee RBL1 (99% identical), dog RBL1 (95% identical), macaque RBL1 (94% identical), rabbit RBL1 (93% identical), pig RBL1 (92% identical), mouse Rbl1 (90% identical), rat Rbl1 (90% identical), guinea pig RBL1 (89% identical), tropical clawed frog rbl1 (68% identical), zebrafish rbl1 (62% identical), Drosophila melanogaster Rbf (27% identical), Drosophila melanogaster Rbf2 (19% identical), and 1 more. Paralogues in human: RBL2 (52% identical), RB1 (23% identical).
Diseases named in the same sentence as RBL1 in open-access papers:
RBL1 is named in the same sentence as 61 diseases in open-access papers, as found by Europe PMC text mining. Sharing a sentence is not in itself a finding about the gene and the disease. The quoted sentences say what the papers report.
retinoblastoma (43 papers, 2005 to 2026). A malignant tumor that originates in the nuclear layer of the retina. "It was later discovered that the related protein RBL1 (also known as p107) protects against tumorigenesis in mice and mutation in both Rb1 and Rbl1 is needed for retinoblastoma development in mice." (PMID 37712424, 2023). "The retinoblastoma tumor suppressor family contains the proteins, pRb, p107, and p130, encoded by the RB1, RBL1, and RBL2 genes, respectively." (PMID 35250950, 2022). "Ablation of Rb1/Rbl2 leads to rapid development of multifocal retinoblastoma while ablation of Rb1/Rbl1 causes more delayed development of unifocal retinoblastoma." (PMID 35368709, 2022). "Co-deletion of RB1, PTEN, and Rbl1 (p107) in mouse retinal progenitor cells caused fully penetrant bilateral retinoblastomas." (PMID 33591981, 2021). "Co-deleting Pten with Rb1 and Rbl1 in mouse retinal progenitor cells (RPCs) causes fully penetrant bilateral retinoblastomas by 30 days and strongly suppresses Rb/E2F-induced apoptosis." (PMID 25907958, 2015). "In order to confirm that the retinoblastoma and brain tumors are clonal outgrowths of cells carrying mutations in both the rb1 and rbl1 gene, we dissected an eye exhibiting retinoblastoma development and a normal looking eye from the injected side of a MDKO tadpole." (PMID 27739525, 2016). "Unlike the penetration of the germline RB1 mutation in human retinoblastoma, mice cannot develop retinoblastoma with similar disruption of the Rb1 gene, even if pRb is completely inactivated, because pRb-related proteins p107 (RBL1) and p130 (RBL2) compensate for functional loss of pRb." (PMID 32824373, 2020). "Thus, like Rbl1/p107, Rbl2/p130 is differentially regulated in mice and humans, which may account for the different mutational events required to initiate retinoblastoma in these species." (PMID 22761580, 2012). "This reflects the expression pattern observed in native retinoblastoma with prominent expression of RBL1 but almost undetectable expression of RBL2, further reinforcing the validity of the retinal organoid model." (PMID 35565295, 2022). "In humans, Retinoblastoma susceptibility gene is a member of a small gene family that includes RB1 (p105/pRb), RBl1 (p107/pRBL1), and RBl2 (p130/pRBL2), whose protein structure are very similar, and that share some overlapping functions." (PMID 32664691, 2020). "A second model by the same group used CRISPR/Cas9-mediated knockout of rb1 and rbl1 genes in Xenopus tropicalis to phenocopy Retinoblastoma, a paediatric tumour of the developing retina." (PMID 30538639, 2018). "Different mouse models are available, all based on genetic deactivation of both Rb1 and Retinoblastoma-like 1 (Rbl1), and each showing different kinetics of retinoblastoma development." (PMID 27739525, 2016). "The retinoblastoma was strongly enriched in two rb1 frameshift deletions (85%; Δ52 and Δ7) and an rbl1 insertion (58%; +36)." (PMID 27739525, 2016). "This implies that the Chx10-Cre; Rb1Lox/Lox; Rbl1−/− mice model, and the five others, are suitable models closely mimicking the molecular background of clinical retinoblastoma." (PMID 27739525, 2016). "By extension, this strongly suggests that modeling retinoblastoma by knocking out Rb1 and Rbl1 in mice is a suitable approach, which we expect to be similar in other animals models, such as Xenopus tropicalis." (PMID 27739525, 2016). "Here, we show by CRISPR/Cas9 techniques that similar to the mouse, neither rb1 nor rbl1 single mosaic mutant Xenopus tropicalis develop tumors, whereas rb1/rbl1 double mosaic mutant tadpoles rapidly develop retinoblastoma." (PMID 27739525, 2016). "We also generated Osx-Cre; Rb1fl/fl; p107-/- mice to test the effect of co-deleting the Rbl1 (p107) gene, a pRB pocket protein family member, because its deletion augments other Rb driven tumors like retinoblastoma in mice." (PMID 26317218, 2015).
retinoblastoma (continued). "High-risk alpha E7 represses the retinoblastoma family of tumor suppressors: RB1 (retinoblastoma), RBL1 (p107), and RBL2 (p130); E7 targets the degradation of RB1, which is tied to the cancer phenotype." (PMID 26470018, 2015). "Similarly, knocking out of Rb1 and Retinoblastoma-like 1 (Rbl1) genes by CRISPR/Cas9 led to retinoblastoma formation in Xenopus tropicalis." (PMID 30109230, 2018). "In contrast, the retinoblastoma showed enrichment of INDELs in both rb1 (80%) and rbl1 (74%) loci." (PMID 27739525, 2016). "Furthermore, over-expression of miR-17-92 clusters with deletion of Rb1 and Rbl1 accelerated the emergence of retinoblastoma with frequent metastasis to the brain in mice." (PMID 25359779, 2014). "Additionally, this retinoblastoma model provides unique possibilities for fast elucidation of novel drug targets by triple multiplex CRISPR/Cas9 gRNA injections (rb1 + rbl1 + modifier gene) in order to address the clinically unmet need of targeted retinoblastoma therapy." (PMID 27739525, 2016). "Experimental evidence implicating RBL1 and RBL2 in tumor suppression has roots in attempts to model retinoblastoma in mice." (PMID 35368709, 2022). "Transcriptome analysis of RB1 knockout organoids and primary retinoblastoma revealed gain of a retinoblastoma expression signature in the organoids, characterized by upregulation of RBL1 (p107), MDM2, DEK, SYK and HELLS." (PMID 35565295, 2022). "The proliferative role of CDK/cyclin proteins, in general, is mediated through the phosphorylation of the major CDK‐substrate, RB1 (Retinoblastoma) tumor suppressor, and its related proteins RBL1 (p107) and RBL2 (p130) [collectively referred to here as pRB]." (PMID 31566717, 2019). "For this rb1, rbl1 and a modifier are targeted by triple multiplex CRISPR/Cas9 and retinoblastomas should be (micro)dissected." (PMID 27739525, 2016). "We show rapid and penetrant retinoblastoma development in X. tropicalis, by co-targeting of rb1 and rbl1 with multiplex CRISPR/Cas9, closely recapitulating the histopathological hallmarks of clinical retinoblastoma." (PMID 27739525, 2016). "When the retinoblastoma tumor suppressor Rb1/Rbl1 is absent in the retina, the development of retinoblastoma is inhibited." (PMID 38955924, 2024). "As we did not detect any retinoblastoma after inactivation of either rb1 or rbl1, we next performed multiplex genome editing by co-injections of two independent pairs of rb1 and rbl1 gRNAs." (PMID 27739525, 2016). "Rbl1 mosaic mutants (n = 5) were raised until 73 days of age, and none developed retinoblastoma distinguishable by gross examination." (PMID 27739525, 2016). "Murine retinoblastoma was first observed in chimeric animals lacking both Rb1 and Retinoblastoma-like 1 (Rb1/Rbl1), however the low recovery of viable chimeras precluded the generation of study-sized populations of retinoblastoma-bearing mice." (PMID 27739525, 2016).
prostate carcinoma (7 papers, 2012 to 2023). A carcinoma that arises from epithelial cells of the prostate gland. "Given that RB-related proteins, RBL1 and RBL2, can functionally compensate for loss of RB in some settings, we investigated whether a similar RBL1/RBL2/E2F/ACSL4 axis exists in human prostate cancer." (PMID 36928314, 2023). "We found that, similar to RB, depletion of RBL1 or RBL2 led to upregulation of ACSL4 and E2F-targeted genes and sensitized prostate cancer cells to ferroptosis induction." (PMID 36928314, 2023). "The latest study validated RBL1, KLF5, SMAD4, and TIMP2 as the direct miR-888 targets in prostate cancer." (PMID 33123477, 2020). "Likewise, a recent study showed that the overexpression of miR-888 increased cellular proliferation and migration by targeting the tumor suppressor genes RBL1 and SMAD4, suggesting the oncogenic role of miR-888 in prostate cancer progression." (PMID 33123477, 2020). "However, homozygous loss of RBL1 or RBL2 was rarely observed in metastatic castration-resistant prostate cancer samples from various data sets, and no positive association was found between ACSL4 expression and inactivation of RBL1 or RBL2." (PMID 36928314, 2023).
breast cancer (5 papers, 2012 to 2024). A primary or metastatic malignant neoplasm involving the breast. "Data mining revealed that RBL2 is more commonly gaining insertions and deletions in breast cancer than RBL1 and pRb, indicating that 275 out of 997 breast tumours had aberrations in the RBL2 locus whereas the corresponding numbers for RBL1 and pRb were 165 and 249, respectively." (PMID 38678032, 2024).
small cell lung carcinoma (5 papers, 2017 to 2025). Small cell lung cancer (SCLC) is a highly aggressive malignant neoplasm, accounting for 10-15% of lung cancer cases, characterized byrapid growth, and early metastasis. "The Rbl1-deleted small cell lung cancers exhibited a higher rate of mediastinal lymph node metastasis and lymphocyte infiltration compared to Rbl2-ablated mice." (PMID 35368709, 2022). "Thus Rbl1 and Rbl2 have tumor suppressor activity in the context of small cell lung cancer, but it is only revealed in the absence of RB1." (PMID 35368709, 2022).
colorectal cancer (4 papers, 2016 to 2025). A primary or metastatic malignant neoplasm that affects the colon or rectum. "The G1 phase‐related gene cyclin D1 was downregulated while the cell cycle inhibitor Rb1, Rbl1, and P21 were upregulated by inhibition of GABABR, which helped us determined that activation of GABABR can significantly promoted colorectal cancer cell proliferation by arrested cell at G1 phase." (PMID 27060477, 2016).
lung carcinoma (4 papers, 2013 to 2021). "We selected seven genes [4 unique genes (E2F6, TFDP1, SUV39H1, and HNRPD) for NSCLC and 3 genes (RBL1, IRF1, and HMGA1) for general events] for validation as diagnostic markers in lung cancer." (PMID 24564251, 2013). "Therefore, RBL1 downregulation and upregulation of miR-17 provide a meaningful mechanism in lung cancer tumorigenesis." (PMID 24564251, 2013). "Therefore, gene RBL1 is a tumor suppressor gene of lung cancer." (PMID 29670664, 2018). "Here, we made the novel observation that in lung cancer and mesothelioma cells, RBL1/p107 levels and phosphorylation are modulated by a complex network of signaling pathways including CaMKs and calpain, the activity of which is Ca2+-dependent." (PMID 34638509, 2021). "The results of initial experiments with the AKT inhibitor AKTi VIII suggested a role of AKT in modulating RBL1/p107 levels/activity in lung cancer and mesothelioma cells, as in fact AKT inhibition affected RBL1/p107 levels as well as phosphorylation." (PMID 34638509, 2021). "Thus, we first tested in A549 lung cancer and MSTO-211H mesothelioma cells whether AKT inhibition by the specific AKT inhibitor VIII (AKTi VIII) might affect also RBL1/p107 protein levels." (PMID 34638509, 2021).
glioma (3 papers, 2015 to 2024). A benign or malignant brain and spinal cord tumor that arises from glial cells (astrocytes, oligodendrocytes, ependymal cells). "In glioma, the expression level of RBL1 is markedly down-regulated in glioma samples, playing a crucial role in glioma tumorigenesis." (PMID 38167011, 2024). "By analyzing the clinical data of 4 glioma patients in Affymetrix chip, RBL1 is isolated as a core gene affecting glioma patient survival and chemotherapy sensitivity." (PMID 38167011, 2024). "In the signature, HDAC1 (HR:1.4938) and RBL1 (HR:1.7148) were deemed a hazard, while RUNX1T1 (HR:0.7349), FKBP3 (HR:0.6382), and PHF21A (HR:0.4956) promoted survival possibilities for glioma patients." (PMID 34540896, 2021).
melanoma (3 papers, 2022 to 2025). A malignant, usually aggressive tumor composed of atypical, neoplastic melanocytes. "In order to confirm the transition of the melanoma cells to a senescent state under vemurafenib treatment, we analysed the expression and evaluated the mRNA levels of cyclin D1 (CCND1) and RBL1." (PMID 40636307, 2025). "In other cancers like melanoma, the frequency of pocket protein paralogue alterations is comparable (melanoma RB1 = 5.6%, RBL1 = 5.9%, RBL2 = 3%)." (PMID 35368709, 2022).
adenoma (2 papers, 2010 to 2025). A neoplasm arising from the epithelium. "The study identified mutations in senescence-associated genes, namely, ATM, PIF1, TELO2, XAF1, and RBL1, in five of twenty subjects with multiple adenomas, indicating germline loss-of-function variants in genes that regulate senescence pathways with the development of serrated adenomas." (PMID 40699620, 2025).
squamous cell carcinoma (2 papers, 2013). A carcinoma arising from squamous epithelial cells. "RBL1 is downregulated and inversely correlates with the histological grade of squamous cell carcinomas and adenocarcinomas." (PMID 24564251, 2013). "Our qPCR validation shows downregulation in all squamous cell carcinoma and adenocarcinoma samples, which supports the previous findings and RBL1's function in tumors." (PMID 24564251, 2013). "The upregulation of RBL1 and downregulation of IRF1 in the microarray analysis was significant in squamous cell carcinoma but was statistically insignificant in adenocarcinoma." (PMID 24564251, 2013). "We found that E2F6, HMGA1, IRF1, and TFDP1 were upregulated and RBL1, SUV39H1, and HNRPD were downregulated or aberrantly expressed in adenocarcinoma and squamous cell carcinoma, which are the sub-types of NSCLC." (PMID 24564251, 2013). "Therefore, combining the microarray and qPCR results, upregulation of E2F6, HMGA1, IRF1, and TFDP1 and downregulation or no expression of SUV39H1, RBL1, HNRPD can be used as diagnostic markers of NSCLC, and, in particular, adenocarcinoma and squamous cell carcinoma." (PMID 24564251, 2013). "Our results suggest that overexpression of HMGA1, E2F6, IRF1, and TFDP1 and downregulation or no expression of SUV39H1, RBL1, and HNRPD in blood is suitable for diagnosis of lung adenocarcinoma and squamous cell carcinoma sub-types of NSCLC." (PMID 24564251, 2013).
brain neoplasm (1 paper, 2016). A neoplasm (disease) that involves the brain. "The brain neoplasm, however, was also heavily enriched for rb1 frameshift deletion (89%; Δ52 and Δ7) and rbl1 insertion (97%; +32)." (PMID 27739525, 2016).
colitis (1 paper, 2024). Inflammation of the colon. "Contrary to the groups of C57BL/6 mice subjected to the induction of experimental colitis where local IL-10 levels were similar to NC, local IL-10 levels remained elevated in recovered BALB/c mice (compared to NC: p ˂ 0.005 for rBL0.1, p ˂ 0.001 for rBL1, rBL10, and PC)." (PMID 38892639, 2024).
colon cancer (1 paper, 2018). "Similarly, five genes including TOP2A, REL, SHH, ROS1, and CHEK2 in colon cancer gene network and three genes including RBL1, MAPK9, and PIK3CA in adenocarcinoma of lung gene network are selected." (PMID 29670664, 2018).
epilepsy (1 paper, 2015). A brain disorder characterized by episodes of abnormally increased neuronal discharge resulting in transient episodes of sensory or motor neurological dysfunction, or psychic dysfunction. "Within the network, many genes are related to inflammation and apoptosis, such as MAPK1, ATM, MYD88, RBL1, TRAF6, PIK3CD, IFNAR2, etc, indicating that these miRNAs may play a role in drug-resistant epilepsy through inflammation and apoptosis." (PMID 25984652, 2015).
eye tumors (1 paper, 2016). "Mosaic double rb1/rbl1 knockout tadpoles (MDKO tadpoles) rapidly developed externally visible eye tumors as early as 36 days post-injection." (PMID 27739525, 2016).
fibrosis (1 paper, 2021). the formation of excess fibrous connective tissue in an organ or tissue in a reparative or reactive process. "Fibrosis is associated with upregulation of RBL1, CDK9, Renin receptor, mitogen-activated protein kinase p38α (Mapk14 gene)." (PMID 34428743, 2021).
gallstones (1 paper, 2025). Solid crystalline precipitates in the biliary tract, usually formed in the gallbladder, resulting in the condition of cholelithiasis. "Together with ceramide‐activated PKCζ nuclear translocation and RBL1‐Sp1 activation, this induces MUC1·5ac hyperproduction, which combines with high CSI to promote gallstone formation." (PMID 39932450, 2025). "Additionally, we uncovered the gallbladder FXR‐miR30c/e‐SDPR axis as a novel mechanism linking caveolae disruption, nuclear PKCζ‐RBL1‐Sp1 signaling and MUC1‐regulated gallstone formation." (PMID 39932450, 2025).
gastric cancer (1 paper, 2017). A primary or metastatic malignant neoplasm involving the stomach. "RBL1 is methylated in patients with intestinal metaplasia, with or without Helicobacter pylori, and in gastric cancer patients." (PMID 28418867, 2017).